MYH7 (myosin heavy chain 7)
Diseases named in the same sentence as MYH7 in open-access papers (continued):
Sharing a sentence is not in itself a finding about the gene and the disease.
cardiac hypertrophy (continued). "We also analyzed myosin heavy chain alpha (Myh6) and myosin heavy chain beta (Myh7), as their expression is altered during cardiac hypertrophy." (PMID 24475304, 2014). "To elaborate on the DNA methylation array results, we selected several DMRs at different gene loci related to cardiac hypertrophy including Mef2c, Tnnt2, Myh6, Myh7, and Gata4 and body weight Ins2 for bisulfite sequencing." (PMID 24475304, 2014). "Analysis of a more specific ontology, cardiac hypertrophy – NF-AT signaling, revealed similar genes as the general hypertrophic cardiomyopathy ontology such as Myh6, Myh7, Tnnt2, Tnni3, and Actc1." (PMID 24475304, 2014). "Myh7 is still expressed in adulthood but an increase in its expression during adulthood is a common feature of cardiac hypertrophy." (PMID 24475304, 2014). "We confirmed by qRT-PCR that adult mice have increased levels of mRNA encoding for atrial natriuretic peptide(NPPA) and β-myosin heavy chain (MYH7), two characteristic mRNAs and proteins that increase in cardiac hypertrophy." (PMID 22912742, 2012). "The ratio of MYH7 to MYH6 was considered as cardiac hypertrophy marker." (PMID 39981966, 2025). "There was also an increase in the expression of cardiac hypertrophy molecular markers, including myosin heavy chain 7 (Myh7 or β-myosin heavy chain, β-Mhc), and natriuretic peptide B (Nppb or Bnp), in KO mice compared with WT animals, although Myh6 (α-Mhc) was not modified." (PMID 40301189, 2025). "The suppression of the PPP in MYH7 Q315R variant mice, alongside the lack of significant myocardial hypertrophy, is consistent with both echocardiographic and histological findings." (PMID 41237118, 2025). "In this cohort, a female patient with mixed apical hypertrophy (25 mm) and fibrosis on the CMR was found to have a pathogenic variant in the myosin light-chain-2 gene, MYL2, along with two VUSs in the MYH7 gene, which may contribute to the apical phenotype." (PMID 40428316, 2025). "miR-208b, intronic to MYH7, is known to regulate cardiac hypertrophy." (PMID 40565220, 2025). "The protein expression of genes associated with cardiac hypertrophy (Anp and Myh7), was also found to be reduced in mice lacking Otud1." (PMID 39309432, 2024). "Furthermore, Q‐PCR results showed that the levels of MYH7, Nppa and Nppb mRNA, which are indicators of cardiac hypertrophy, were significantly increased in the CIH group and subsequently reduced in the CIH + cTNT‐FPN1 group." (PMID 39054575, 2024). "Cardiac hypertrophy was assessed by measuring the ratio of hypertrophy genes Myh7: Myh6." (PMID 39062999, 2024). "In addition, the raising of heart weight/body weight (HW/BW) further provides evidence for myocardial hypertrophy within the MYH7 R453C piglets." (PMID 38862020, 2024). "LncRNA MHRT was a heart‐specific, cardioprotective antisense lncRNAs localized within myosin heavy chain 7 (Myh7) locus, and reduced expression of lncRNA MHRT in cardiac tissue has been associated with the accelerated progression of cardiac hypertrophy and heart failure." (PMID 39641229, 2024). "Further evidence of the development of cardiac hypertrophy and cardiomyopathy in Mrps5cKO mice includes the upregulation of the hypertrophy and disease marker genes (Nppa, Nppb, and Myh7) and fibrosis marker genes (Col1a1, Col1a2, and Col1a3) in Mrps5cKO hearts." (PMID 36949106, 2023). "In addition, DBZ markedly attenuated the increase in Ang II-induced transcription of Nppa and Myh7, markers of myocardial hypertrophy." (PMID 35185583, 2022). "Therefore, the study of these two MYHC molecules and their genes, MYH6 and MYH7, will give us further insights into cardiac hypertrophy and potentially help us improve the diagnosis and treatment of various other cardiomyopathies." (PMID 36157891, 2022). "Also, the cardiac hypertrophy in Clk4-cKO mice was indicated by dramatic increases in the expression of fetal cardiac genes such as Nppa, Nppb, and myosin heavy chain 7 (Myh7)." (PMID 35907876, 2022).
cardiac hypertrophy (continued). "Similarly, heart expression of the cardiac hypertrophy marker Myh7 was negatively correlated with aortic valve area, and positively correlated with Vmax and mean pressure gradient (r = −0.7106, r = 0.7610 and r = 0.8201, respectively; p < 0.05)." (PMID 36414704, 2022). "In the case of TCF7L2, it is found to be involved in cardiac hypertrophy through the Wnt/β-catenin signaling pathway, where it modulates the chromatin environment and regulates the expression of the slow Myh7 (MyHC-1) and the Wnt/β-catenin target, the Myc gene." (PMID 34752468, 2021). "To test the hypothesis that an increase in cardiac miR-208b indicates heart hypertrophy, we analyzed the expression of miR-208b and myh7 in hearts from mice treated with either angiotensin II or isoprenaline for three or two weeks, respectively." (PMID 34201741, 2021). "When cardiomyocytes are stressed, Brg1 expression increases, forms a complex with HDAC/PARP, and outruns the inhibitory effect of Mhrt779 so that it can inhibit myh6 and promote expression of myh7 promoting hypertrophy; and inhibition of Mhrt779 prevented experimental cardiac hypertrophy in mice." (PMID 34207151, 2021). "In addition, gene expression levels of cardiac hypertrophy markers Myh7/Myh6, Nppa, and Nppb were significantly lower in the hearts from Mkp-5-/- mice as compared with Mkp-5+/+ controls at 4 weeks after TAC." (PMID 34992607, 2021). "Furthermore, YTHDF2 protein interacts with Myh7 (beta-myosin heavy chain) mRNA, an important cardiac hypertrophy marker, to induce Myh7 mRNA decoy in an m6A-dependent manner, thereby inhibiting HF development." (PMID 34266473, 2021). "Furthermore, we found that YTHDF2 suppresses cardiac hypertrophy via Myh7 mRNA decoy in an m6A-dependent manner." (PMID 34266473, 2021). "However, ISO or PHE stimulation significantly increased YTHDF2 protein interacting with Myh7 (beta-myosin heavy chain) mRNA, an important cardiac hypertrophy marker, in an m6A-dependent manner." (PMID 34266473, 2021). "Finally, AF patients showed a drastically increase of myosin heavy chain 7 (MYH7) protein levels, a hallmark of cardiac hypertrophy." (PMID 32784971, 2020). "Similarly, B38-CAP treatment significantly suppressed the increased expression of mRNA associated with cardiac hypertrophy, such as ANF (atrial natriuretic factor), BNP (brain natriuretic peptide), and β-myhc (β-myosin heavy chain, Myh7) in the TAC mice." (PMID 32103002, 2020). "In addition, upregulated β-myosin expression (β-MHC, encoded by MYH7), accompany with downregulated α-myosin expression (α-MHC, encoded by MYH6) is a sensitive indicator of cardiac hypertrophy." (PMID 33195237, 2020). "Whether the increased Myh6 and Myh7 expression in vitro and in vivo results from increased occupancy of the promoters of these genes by the P-TEFb complex or is simply reflecting cardiac hypertrophy remains an open question." (PMID 27270731, 2016). "Similarly regulated transcripts between previous studies utilizing TAC-induced cardiac hypertrophy and this study include Acta1, MybpC2/3, Actn2, and Myh7 among others indicating an appropriate hypertrophic gene transcriptional response in WT mice." (PMID 26192751, 2015). "In line with this, HW/BW ratio indicated that RMST silencing was able to reverse cardiac hypertrophy, which was also confirmed by a decrease in mRNA expression of hypertrophy-related genes, including natriuretic peptide precursor A (Nppa) and β myosin heavy chain 7 (Myh7)." (PMID 37441584, 2023). "Moreover, the immunofluorescence staining of WGA and the mRNA expression of hypertrophy markers (included atrial natriuretic peptide/ANP, brain natriuretic peptide/BNP, myosin heavy chain 7/MYH7) together proved that HucMSCs administration attenuated cardiac hypertrophy on day 28 after MI." (PMID 35690805, 2022).
cardiac hypertrophy (continued). "Likewise, the dynamic changes of miR-21 were associated with an upregulation of myocardial injury markers including B-type Natriuretic Peptide (BNP) and A-type Natriuretic Peptide (ANP) but cardiac hypertrophy-related gene myosin heavy chain 7 (MYH7) dropped in late phase of rats subjected to AVS." (PMID 35159373, 2022). "The ratio of MYH7 to MYH6 was also upregulated in mutant cells, which was considered as cardiac hypertrophy marker." (PMID 39981966, 2025). "Prior research indicates that GATA4, a nuclear transcription factor, facilitates the expression of hypertrophic genes such as MYH7 and BNP, which ultimately contribute to myocardial hypertrophy." (PMID 40753540, 2025). "Consistent with cardiomyocyte hypertrophy, qPCR showed increased mRNA expression of cardiac hypertrophy markers (ANP, BNP and MYH7) and decreased mRNA expression of MYH6 in PD‐iCMs." (PMID 37916452, 2024). "Here, we generated transgenic MYH7 R453C and MYH6 R453C piglets and found both developed typical cardiac hypertrophy." (PMID 38862020, 2024). "We examined cardiac hypertrophy-related genes and found that the mRNA levels of BNP (Natriuretic Peptide B), Myh7 (Myosin Heavy Chain 7), and Gata4 (GATA Binding Protein 4) were significantly up-regulated in maternal DHT-treated group." (PMID 37642904, 2024). "Knocking out the expression of HDAC2 in a Hod-Tg-Hdac−/− mice prevented cardiac hypertrophy by inhibiting the upregulation of hypertrophic genes, atrial natriuretic factor (ANF), Myh7 (β-MHC), and Acta1 (α-smooth muscle actin)." (PMID 38427976, 2024). "In addition, ISO led to an increase in mRNA level of classical-cardiac-hypertrophy- and stress-related genes in the left ventricle, particularly under Ppp2r5d-knockdown conditions, including atrial natriuretic peptide (Nppa), brain natriuretic peptide (Nppb), and myosin heavy chain (Myh7)." (PMID 39200351, 2024). "In cardiac hypertrophy and the fibrotic response, the JAK2–STAT3 signaling pathway activates TGFB, COL1A1, and MYH7 transcription, contributing to cardiac remodeling and dysfunction." (PMID 39349833, 2024). "The results showed that with the continuous maturation of cardiomyocytes, the MYH7/MYH6 ratio of KO hiPSC-CMs was gradually increased compared with WT hiPSC-CMs, and KO hiPSC-CMs showed a pathological phenotype of myocardial hypertrophy." (PMID 38072986, 2023). "Both groups of mice developed a comparable degree of cardiac hypertrophy in response to TAC, as shown by similarly enhanced HW/TL ratio, embryonic gene expression (decrease in Myh6 and Atp2a2, increase in Myh7 and Acta1 mRNA) and cardiomyocyte size." (PMID 35013221, 2022). "The expression of cardiac hypertrophy marker genes (BNP and MYH7) was significantly upregulated in VASN−/− mice compared with VASN+/+ mice (Figure 3B3‐B4)." (PMID 34854218, 2022). "The expression of TGF-β and p-Smad3 reduced after QYYY treatment, as well as MYH7 and MYH7/MYH6, which demonstrated QYYY granules can downregulate the key genes involved in cardiac fibrosis and cardiac hypertrophy." (PMID 34484396, 2021). "In the TAC group, MYH7, ANP, and BNP expression levels were increased, indicating that pressure overload successfully induced cardiac hypertrophy in the mouse TAC model." (PMID 34054926, 2021). "We further observed the effects of miR-26a-5p on cardiac hypertrophy-related markers including ANP, ACTA1 and MYH7." (PMID 33240671, 2020). "Further supporting evidence showed a decrease in hypertrophy gene levels of myosin heavy chain 7 (Myh7), natriuretic peptide A (Nppa), and natriuretic peptide B (Nppb) in YAP/TAZ-dKO infarcted heart, suggesting an improvement in cardiac hypertrophy after MI." (PMID 33264286, 2020). "miR-26a-5p dramatically promoted PE-induced increase in cardiac hypertrophy-related markers including ANP, ACTA1 and MYH7." (PMID 33240671, 2020). "GSK3β overexpression significantly reversed the expression of cardiac hypertrophy-related markers including ANP, ACTA1 and MYH7." (PMID 33240671, 2020).
cardiac hypertrophy (continued). "qRT-PCR showed that cardiac hypertrophy-related markers including ANP, ACTA1 and MYH7 were significantly elevated in miR-26a-5p agomir group compared to controls." (PMID 33240671, 2020). "Subsequent studies indicate that cardiac hypertrophy usually accompanies upregulation of BNP and MYH7 and/or downregulation of MYH6 expression levels." (PMID 28479925, 2017). "The transcripts of cardiac hypertrophy markers including ANP, BNP and Myh7 were also significantly up-regulated in the heart tissues of KLK8 transgenic rats." (PMID 26823023, 2016). "For instance, cardiac hypertrophy is usually accompanied by re-expression of the fetal genes such as ANP, BNP and MYH7, which are generally repressed in the adult heart." (PMID 27258257, 2016). "It was found that intra-cardiac KLK8 gene delivery led to a significantly increase in the transcripts of cardiac hypertrophy markers including ANP and Myh7." (PMID 26823023, 2016). "Cardiac fetal genes (NPPA, NPPB, MYH6, MYH7 and ACTA1) are usually only expressed during fetal life and re-expression of these genes in adult life is an indicator of pathologic cardiac hypertrophy." (PMID 25051449, 2014). "Lrrc10−/− hearts exhibit significant induction of the fetal genes ANF (atrial natriuretic factor, Nppa), β-MHC (β-myosin heavy chain, Myh7), and BNP (brain natriuretic peptide, Nppb), indicating pathological cardiac hypertrophy." (PMID 23236519, 2012). "In line with these functional data, we also observed that GDM exposure increased the protein levels of cardiac hypertrophy markers (ANP, BNP, and MYH7) and exacerbated TAC-induced cardiac hypertrophy, as evidenced by an increased HW/BW ratio, larger cardiomyocyte size, and greater cardiac fibrosis." (PMID 41509912, 2026). "Myocardial hypertrophy was evident, as shown by enlarged cardiomyocyte cross-sectional area, elevated LVW and LVW/TL, and upregulation of hypertrophy-related genes, including Nppa, Nppb, and Myh7." (PMID 41008530, 2025). "Third, the cardiac hypertrophy in Atp6v0d1AKO cardiomyopathy is not accompanied by activation of the fetal genes, Nppa and Myh7, even when the contractile function is impaired." (PMID 38505620, 2024). "Furthermore, real‐time PCR results suggested that NLRP3 deletion suppressed the expression of cardiac hypertrophy‐related genes (ANP, BNP, and Myh7) and cardiac fibrosis‐related genes (Col1a1 and CTGF) in obese hearts." (PMID 39604027, 2024). "Cardiac hypertrophy and remodeling are also crucial early adaptative steps (before becoming pathological), which are accompanied by the re-expression of the fetal gene program comprising NPPA, ACTA1, and MYH7." (PMID 37445625, 2023). "P300 overexpression in mouse cardiomyocytes stimulates the expression of the GATA4-dependent genes related to cardiac hypertrophy, including natriuretic peptide precursor A(Nppa, mediating the translation of ANP), prepro-endothelin-1(ET-1), and β-myosin heavy chain (Myh7)." (PMID 35958418, 2022). "In addition, cardiac hypertrophy-related GATA4-dependent genes expression, including Nppa and Myh7, also enhance the reaction to the adverse stimulation." (PMID 35958418, 2022). "Furthermore, when CF-KO mice were compared to WT controls, pathological cardiac hypertrophy post-MI was significantly reduced, as demonstrated by lower cardiomyocyte cross-sectional area (CSA) and hypertrophic marker gene (Nppa, Nppb, and Myh7) mRNA levels." (PMID 35966575, 2022). "In addition, mRNA levels of classical markers of cardiac hypertrophy (ANP, BNP, and MYH7) were elevated in TAC-operated mice and were reduced by FGF20 overexpression." (PMID 35351862, 2022). "In addition, overexpression of FST promoted cardiac hypertrophy with an unchanged expression of atrial natriuretic peptide (ANP) and the ratio of myosin heavy chain-β/myosin heavy chain-α (MYH7/MYH6)." (PMID 34385917, 2021).
cardiac hypertrophy (continued). "In concert with the cardiac hypertrophy observed in echocardiography and histopathological examination, RT-qPCR showed higher myocardial mRNA expression levels of Myh7 and ANP, indices of cardiac hypertrophy and pressure overload, in offspring with MFE than those in offspring without." (PMID 34579143, 2021). "In the ventricular hypertrophy phase without HF, we detected that myh7 gene expression (gene responsible for the increase in β-MHC) tended to increase; preventive exercise did not have an effect on this change." (PMID 34495964, 2021). "Furthermore, miR-26a-5p agomir significantly promoted cardiac hypertrophy-related markers including ANP, ACTA1 and MYH7." (PMID 33240671, 2020). "While specific response to beta-blocker treatment is not currently a documented feature of MYH7 HCM, beta-blocker treatment in childhood HCM has been associated with a reduction in cardiac hypertrophy and improved survival." (PMID 26337809, 2015). "ACTA1, MYH7, and SERCA2 are well-known markers for cardiac hypertrophy." (PMID 26108756, 2015). "Interestingly, a T3-induced decrease in MYH7 and increase in MYH6 levels are similar to their gene expression profiles found in physiological cardiac hypertrophy induced by exercise, while cardiac function has been shown to be reduced in hypothyroidism." (PMID 24781449, 2014). "However, genes associated with cardiac hypertrophy, including GATA4, MYH7, and NPPA, were not differentially expressed in the LV." (PMID 36924351, 2025). "On the contrary, overexpression of Foxo6os in Ang II‐treated cardiomyocytes could postpone the progression of cardiac hypertrophy, manifesting a significant reduction in the levels of ANP, BNP, and MYH7 compared to the control group, and further confirmed by immunofluorescence (IF) staining." (PMID 40548957, 2025). "Similarly, in cardiomyocytes, Ythdf2 alleviates cardiac hypertrophy by modulating Myh7 mRNA stability, rather than mRNA transition, highlighting a context-specific role of Ythdf2." (PMID 40824213, 2025). "In line with morphological findings, we found that mRNA levels of ANP, BNP, and cardiac β-MHC (MYH7) established indicators of cardiac hypertrophy, do not increase in cardiomyocytes long-term treated with postoperative HiR-REM plasma exosomes during exposure to AngII." (PMID 35966562, 2022). "Furthermore, we tested the mRNA expressions of cardiac hypertrophy markers, ANP and Myh7 in vitro." (PMID 35311628, 2022). "In contrast to these data, overexpression of OGA in cardiomyocytes (cmOGA-Tg) results in reduced O-GlcNAcylation and slight cardiac hypertrophy that is not accompanied by enhanced expression of natriuretic peptide alpha (Nppa) and myosin heavy chain 7 (Myh7; markers of pathologic hypertrophy)." (PMID 36359905, 2022). "This possible adaptation in myh7 gene expression may reflect a more economical energetic phenotype, as beta-MHC can generate a cross-bridge force that provides more economical energy consumption in the ventricular hypertrophy phase)." (PMID 34495964, 2021). "Furthermore, we detected whether YTHDF2 interacts with the mRNAs of cardiac hypertrophy makers, including ANP (atrial Natriuretic Peptide), BNP (brain natriuretic peptide), and MYH7 by RIP." (PMID 34266473, 2021). "Furthermore, studies in rodents with pressure overload-induced cardiac hypertrophy showed that MYH7 genes were greatly expressed with smaller cardiomyocytes as opposed to larger cardiomyocytes, and that MYH7 was markedly expressed in middle layers of the myocardium." (PMID 35548426, 2022). "Also, compared with control, one μM WIN did not increase MYH6 and MYH7 mRNA levels, genes that, when upregulated, may indicate cardiac hypertrophy in vitro." (PMID 34707939, 2021). "Furthermore, we found that knockdown of MYH7 significantly inhibited ISO or PHE-induced myocardial hypertrophy, and overexpression of YTHDF2 did not further alleviate myocardial hypertrophy." (PMID 34266473, 2021).
cardiac hypertrophy (continued). "But, ISO stimulation did not affect the interaction of YTHDF2 and MYH7, suggesting YTHDF2 may be not affect cardiac hypertrophy by interacting with MYH7." (PMID 34266473, 2021).